GAPT (GRB2 binding adaptor protein, transmembrane)
Description:
Negatively regulates B-cell proliferation following stimulation through the B-cell receptor. May play an important role in maintenance of marginal zone (MZ) B-cells (By similarity).
Synonyms: C5orf29; FLJ33641
Tractability: Antibody: UniProt places it where antibodies can reach, with high confidence; its Gene Ontology location is reachable by antibodies, with high confidence; UniProt predicts a signal peptide or a membrane-spanning region; the Human Protein Atlas places it where antibodies can reach. PROTAC: its protein half-life has been measured.
Gene: Protein-coding gene on chromosome 5 (58,491,435 to 58,497,090, forward strand). Ensembl gene ENSG00000175857.
Subcellular location: Cell membrane
Subcellular location (Human Protein Atlas): Plasma membrane; Golgi apparatus; Vesicles
Gene Ontology:
Biological process: B cell homeostasis; B cell proliferation involved in immune response
Cellular component: plasma membrane; membrane
Genetic constraint (gnomAD): Loss-of-function variants: 1 observed, 1.4 expected, observed/expected ratio (o/e) 0.72, 90% interval 0.22 to 1.85. That is too few expected variants to judge how well the gene tolerates losing a copy. Missense variants: 194 observed, 187.76 expected, observed/expected ratio (o/e) 1.03, 90% interval 0.92 to 1.16. Synonymous variants: 78 observed, 70 expected, observed/expected ratio (o/e) 1.11, 90% interval 0.93 to 1.35.
Homologues: Orthologues: chimpanzee GAPT (99% identical), macaque GAPT (93% identical), rabbit GAPT (67% identical), dog GAPT (66% identical), pig GAPT (66% identical), mouse Gapt (55% identical), rat Gapt (55% identical).
Diseases named in the same sentence as GAPT in open-access papers:
GAPT is named in the same sentence as 8 diseases in open-access papers, as found by Europe PMC text mining. Sharing a sentence is not in itself a finding about the gene and the disease. The quoted sentences say what the papers report.
Cognitive impairment (1 paper, 2020). Abnormal cognition is characterized by deficits in thinking, reasoning, or remembering. "Eight months and three months after administration with GAPT, spatial learning function and memory abilities were significantly enhanced, suggesting that GAPT could prevent cognitive impairments and protect learning and memory function in an AD‐like rat model." (PMID 32174034, 2020).
Hepatic steatosis (1 paper, 2015). Steatosis is a term used to denote lipid accumulation within hepatocytes. "Consistent with previous reports, tunicamycin treatment decreased the expression of lipogenic genes including FAS, ACC1, and GAPT despite the presence of hepatic steatosis." (PMID 26540043, 2015).
nasal polyp (1 paper, 2022). "Expression levels of ALOX5AP, AQP9, CCL13, EMR3, F13A1, GAPT, and NCF2 were significantly higher in nasal polyp samples from ACRSwNP patients compared with the expression levels in samples from healthy subjects." (PMID 36059464, 2022).
uveitis (1 paper, 2025). An inflammatory process affecting a part of or the entire uvea. "Machine learning identified IFN-associated genes as robust predictors, while linear discriminant analysis pinpointed CCR2, CD180, GAPT, and PTGS2 as key risk factors in isolated uveitis and CA1, SIAH2, and PGS in systemic disease-associated uveitis." (PMID 40270958, 2025). "The genes that showed a significantly increased risk ratio for uveitis in the uveitis only group, and were upregulated in patients, included CCR2, CD180, GAPT, and PTGS2." (PMID 40270958, 2025). "For instance, in the uveitis only group, the genes KLHL21, MYLIP, ZNFX1, PDE4A, TNFRSF21, and N4BP2L2 were downregulated, while METTL72, GAPT, CD180, CCR2, and TLR7 were upregulated when comparing uveitis patients with healthy controls." (PMID 40270958, 2025).
cancer (3 papers, 2015 to 2025). A tumor composed of atypical neoplastic, often pleomorphic cells that invade other tissues. "A few genes associated with disease were identified, including BMP and activin membrane-bound inhibitor (BAMBI), which has been associated with various pathologies, including cancer, and also poorly studied genes of potential interest like GRB2-binding adaptor protein, transmembrane (GAPT)." (PMID 25565328, 2015). "Therefore, we believe that GAPT and GRAP2 are involved in the activationof MAPK and growth factor-induced cell proliferation and differentiation, which areoften associated with the development of cancer." (PMID 29489999, 2018).
tumor (1 paper, 2022). "In the HPA database, protein expressions of the seven genes (ADAMTS8, CCR2, CYSLTR2, FAM129C, FCER1A, GAPT, PKHD1L1, and ZNF831) were markedly low in tumor tissues with less intense antibody staining and fewer stained cells in LUAD." (PMID 36033829, 2022).
GAPT also shares sentences with these, for which no sentence is quoted: memory impairment (1 paper); myocardial infarction (1).